HMGB1 (high mobility group box 1)
Diseases named in the same sentence as HMGB1 in open-access papers (continued):
Sharing a sentence is not in itself a finding about the gene and the disease.
liver fibrosis (continued). "Together, our findings indicate that HMGB1 is a key mediator of schistosomotic granuloma formation and liver fibrosis and may represent a useful target for the treatment of schistosomiasis." (PMID 30258438, 2018). "Taken together, our findings indicate that HMGB1 is a key mediator of schistosomotic granuloma formation and liver fibrosis and may represent an outstanding target for the treatment of schistosomiasis." (PMID 30258438, 2018). "Importantly, infected mice that were treated with DIC or GZR to inhibit HMGB1 pro-inflammatory activity showed a significant increase in survival and a reduction of over 50% in the area of liver fibrosis." (PMID 30258438, 2018). "Although we cannot describe at present the exact molecular mechanism by which hepatocyte HMGB1 signals for the pathogenesis of schistosomotic liver fibrosis, the alarmin activity of HMGB1 seems to be a key factor for the typical exacerbation of the immune responses against the eggs." (PMID 30258438, 2018). "We envision a model where anti-HMGB1 drugs would lead to an efficacious control of schistosomotic liver fibrosis, as follows: during acute schistosomiasis, secreted egg toxins, and antigens trigger a potent immune reaction and inflammatory response that lead to hepatic tissue damage." (PMID 30258438, 2018). "Besides, recent researches have demonstrated that HMGB1/autophagy pathway is involved in several disease models, such as liver fibrosis, Parkinson’s disease and so on." (PMID 30526602, 2018). "While the hepatocytes of mice with acute schistosomiasis are certainly the main source of extracellular HMGB1, HMGB1 from the eggs trapped in the liver can also be released, and could then, contribute to a lesser extent, to liver fibrosis." (PMID 30258438, 2018). "Accumulating evidence indicates that HMGB1 is closely involved in fibrotic diseases, including lung fibrosis, cystic fibrosis, liver fibrosis and pulmonary fibrosis, whereas the inhibition of HMGB1 signaling can act against experimental models of fibrotic disorders." (PMID 29403377, 2017). "We hypothesized that CA might exert anti-liver fibrosis properties through an HMGB1-related pathway, and the results of the present study showed that CA treatment significantly protected against hepatic fibrosis in a bile duct ligation (BDL) rat model." (PMID 29403377, 2017). "Furthermore, icariin, which is used to treat erectile dysfunction, has been shown to reduce liver fibrosis in a thioacetamide-induced liver fibrosis model by antagonizing the increase in HMGB-1 in addition to other mechanisms." (PMID 28771195, 2017). "Based on the miRNA database and our preliminary experiment, we found that miR-29b-3p might play a key role in control of HMGB1 expression in BDL-induced liver fibrosis." (PMID 29403377, 2017). "In summary, our data indicate that the miR-29b-3p/HMGB1/TLR4/NF-κB signaling pathway might be essential for liver fibrosis and that CA could be a promising therapeutic agent in liver fibrosis by modulating the miR-29b-3p/HMGB1/TLR4 signaling pathway." (PMID 29403377, 2017). "Emerging evidence indicates that HMGB1, a pluripotent mediator, contributes to many fibrotic diseases such as CF, liver fibrosis and progressive PF, indicating that HMGB1 may be a promising therapeutic target for such diseases." (PMID 25284457, 2014). "Another research has shown that HMGB1 is up-regulated during liver fibrosis in rats and its expression is closely related to collagen deposition, while inhibition of HMGB1 expression by small interfering RNA (siRNA) inhibits the synthesis of α-SMA and collagen in transfected HSCs." (PMID 25284457, 2014). "Therefore, targeting the signaling pathway between HMGB1 and its receptors may provide a new approach to alleviate liver fibrosis." (PMID 41154556, 2025).
liver fibrosis (continued). "A stable nucleic acid–lipid particle delivery system of mannose-modified HMGB1-siRNA (mLNP-siHMGB1) targets hepatic macrophages via mannose receptor-mediated targeting, thereby silencing HMGB1 protein expression and inhibits the activation of HSCs for the treatment of liver fibrosis." (PMID 37029392, 2023). "Hence, HMGB1 might be a critical regulator in liver fibrosis and inhibition of HMGB1 might be an effective approach for anti-inflammatory therapy of liver fibrosis." (PMID 32425800, 2020). "Therefore, we concluded that CA might target miR-29b-3p to inhibit HMGB1 expression in BDL-induced liver fibrosis." (PMID 29403377, 2017). "Indeed, blocking HMBG1 with small interfering RNA in a murine model of liver fibrosis inhibited collagen production, whereas the injection of recombinant HMGB1 into mice could induce lung pathologies similar to that observed in cystic fibrosis." (PMID 26247017, 2015). "In addition, patients with low hepatic fibrosis also showed elevated serum levels of HMGB-1." (PMID 21507210, 2011). "It is important to note that the aberrant increase in ROS levels associated with miR-200a dysregulation leads to increased expression of HMGB1 and TGF-β1-mediated α-SMA in hepatic fibrosis." (PMID 39853531, 2025). "Isochlorogenic acid and chlorogenic acid can inhibit the protein expression of HMGB1 and TLR4, suppress the overexpression of α-SMA in HSCs, and prevent HSCs activation, thereby alleviating liver fibrosis." (PMID 41154556, 2025). "GA has the ability to inhibit cardiac fibrosis triggered by isoproterenol (ISO) via inhibiting the HMGB1/TLR2 signaling pathway, similar to its effect on liver fibrosis." (PMID 39008169, 2024). "Among the viral molecules encoded by the virus, the significance of the multifunctional protein HBX in the development of hepatic fibrosis by modulating TGF-β, CTGF, HMGB1, Wnt5α, and exosomes in hepatocytes has been revealed." (PMID 37041599, 2023). "Inhibition of NLRP3 by MCC950 ameliorates age‐ and alcohol‐induced liver fibrosis by decreasing inflammatory cell infiltration and hepatocyte‐derived stress signaling—ASK1 and HMGB1." (PMID 36999514, 2023). "HMGB1 promotes the proliferation and activation of HSCs to promote liver fibrosis during SSLF progression, and high levels of HMGB1 at the injury site recruit fibroblasts, endothelial cells, and smooth muscle cells to promote tissue injury repair." (PMID 36389166, 2022). "Inhibiting the expression of HMGB1 by interference methods or antagonists, or suppressing downstream signaling pathways, such as HMGB1/RAGE, are potential strategies to treat schistosome-induced liver fibrosis." (PMID 35335612, 2022). "The beneficial effects of hepatokines include 1) improvement of insulin sensitivity (FGF21); 2) prevention of liver fibrosis (FGF21, HMGB1, PST, AHSG and SERPINF1) and 3) reduction of inflammation and lipid accumulation (FGF21, HMGB1 and LECT2)." (PMID 36267567, 2022). "The study also demonstrated that AR was potent for downregulating the expression of HMGB1/RAGE/cJun pathway and HMGB1/TLR4/NF-κB pathway, thus protecting rats against CCl4-induced liver fibrosis." (PMID 33790974, 2021). "It has been shown that HMGB1 is necessary for hepatic stellate cell activation and participates in HBV-related liver fibrosis progression through its interaction with RAGE and autophagy-inducing effects." (PMID 34458256, 2021). "The interaction of HMGB1 to TLR4 activates an inflammatory response and has been indicated to participate in liver fibrosis." (PMID 32425800, 2020). "In multiple experimental models of mouse liver fibrosis attributed to DILI, cholestasis, ASH, or NASH, elevated expression and release of HMGB1 are induced." (PMID 31731454, 2019). "HMGB1 also stimulates the HSC migration in vitro and in vivo, a critical event driving the progression of liver fibrosis." (PMID 31731454, 2019).
liver fibrosis (continued). "This trend gained further strength in animal-model-based study where a HMGB1 inhibitor was able to downregulate the production of the profibrotic cytokines IL4, IL-5, and IL-13 and significantly reverse (over 50%) liver fibrosis." (PMID 30546364, 2018). "In the study of the treatment of liver fibrosis, curcumin is effective in preventing liver fibrosis partly because of reducing TLR2, TLR4 and HMGB1 expression by inhibiting pro-inflammatory mediators and HSCs activation." (PMID 25284457, 2014). "In addition, GATA-3 was shown to regulate microRNA-370/high mobility group box 1 (miR-370/HMGB1) signaling pathway, promoting autophagy and hepatic stellate cell activation, which contributes to liver fibrosis." (PMID 41514930, 2025). "The increased HMGB1 level in liver tissue of KOSJ group being significantly lower than that of WTSJ mice further demonstrates that PKCλ/ι knockout effectively reduces the percentage of dead liver cells and thereby lessens the degree of hepatic fibrosis." (PMID 35505421, 2022). "HMGB1 mediates p65/miR-146b signaling and inhibits HNF1A to regulate hepatic fibrosis." (PMID 36267567, 2022). "Combined with another literature indicating that HMGB1 might induce TGF-β1 expression in liver fibrosis, as well as our experiment data, we proposed that iExosiRNA−OPN could down-regulate TGF-β1 expression via HMGB1." (PMID 36120332, 2022). "It is reported that the binding of extracellular HMGB1 to TLR4 could activate NF-κB signaling to induce inflammation and aggravate liver fibrosis." (PMID 33790974, 2021). "It has been reported that HMGB1 could increase collagen type I production in HSCs via the receptor for advanced glycation end-products (RAGE), leading to liver fibrosis." (PMID 35187072, 2021). "Therefore, we tested the expression levels of HMGB1, TLR4, Myd88, and NF-κB p65, which are the key targets of this signaling pathway in liver fibrosis rats." (PMID 33790974, 2021). "Transforming growth factor-beta (TGF-β) family of cytokines could also been driven by HMGB1 in renal fibrosis, while proinflammatory cytokines and angiogenic factors could directly stimulate the HSC activation in liver fibrosis." (PMID 31933629, 2019). "Of note, high levels of HMGB1 were previously detected in the sera of patients suffering from hepatic fibrosis, thus suggesting that HMGB1 is an important and reliable non-invasive marker of the level of fibrosis in patients with hepatitis B." (PMID 30258438, 2018). "Also, in vivo in a setting of hepatic fibrosis in rats reduced ALT, AST, IL-6 and HMGB1 values were found after EP treatment compared to the control group accompanied by decreased mRNA levels of TLR4 and NF-κB." (PMID 29420582, 2018). "Collectively, the results demonstrate that a miR-29b-3p/HMGB1/TLR4/NF-κB signaling pathway, which can be modulated by CA, is important in liver fibrosis, and indicate that CA might be a prospective therapeutic drug for liver fibrosis." (PMID 29403377, 2017). "The HMGB1/TLR4/NF-κB signaling pathway induces the proliferation, migration and pro-fibrotic effects of HSCs and enhances the related collagen expression and pro-fibrotic cytokine production in liver fibrosis." (PMID 29403377, 2017). "Therefore, CA increases miR-29b-3p to inhibit the HMGB1/TLR4/NF-κB pathway, thereby attenuating BDL-induced liver fibrosis." (PMID 29403377, 2017). "Peritumoral HMGB1 expression had prognostic value in HCC with cirrhosis, suggesting that peritumoral HMGB1 might show promise as new biomarker to predict HCC progression and potential therapeutic targets in HCC and liver fibrosis." (PMID 27836008, 2016). "In vitro experiments demonstrated that quercetin treatment led to decreased expression of TGF-β1, α-SMA, HMGB1, TLR2/TLR4, and NF-κB p65 proteins in COL1α1 mRNA, suggesting that quercetin may inhibit HSCs activation and improve liver fibrosis by modulating the HMGB1/TLR/NF-κB signaling pathway." (PMID 39185304, 2024).
liver fibrosis (continued). "Interestingly, in the context of autophagy-deficiency in hepatocytes, which presented robust liver injury and fibrosis, Hmgb1 deletion did not affect liver fibrosis." (PMID 31731454, 2019). "Therefore, the HMGB1/TLR4/NF-κB signaling pathway plays a pivotal role in liver fibrosis, and modulation of this signaling pathway is an appealing strategy for the inhibition of liver fibrosis." (PMID 29403377, 2017). "Serum high mobility group box 1 protein (HMGB1) is a proinflammatory molecule that could potentially serve as a biomarker for non-alcoholic fatty liver disease (NAFLD) and non-alcoholic steatohepatitis (NASH) due to its correlation with degree of liver fibrosis." (PMID 29095942, 2017). "Nonetheless, how HMGB1 expression and release (active or passive) is enhanced in NAFLD is less clear, and whether the extracellular HMGB1 affects the downstream liver pathologies other than inflammation, such as hepatic fibrosis or ductular reactions, has not been examined." (PMID 31731454, 2019).
prostate carcinoma (67 papers, 2010 to 2025). A carcinoma that arises from epithelial cells of the prostate gland. "In a further study, The single nucleotide polymorphisms of HMGB1 were identified to be correlated with adverse clinical outcomes in prostate cancer, including higher D’Amico classification, higher pathologic Gleason subgroups, and higher pathologic stage." (PMID 40969278, 2025). "PCAF also induces acetylation of HMGA1 proteins in PC-3 human prostate cancer cells and acetylates HMGB1, which in turn regulates the release of HMGB1 and is linked to the cellular inflammatory response." (PMID 39554048, 2025). "Conversely, HMGB1 silencing diminishes cell growth in LNCaP prostate cancer cells, and the downregulation of RAGE by siRNA causes the inhibition of prostate tumors in nude mice." (PMID 38542079, 2024). "The association between HMGB1 and autophagy is in favor of triggering gemcitabine resistance of prostate cancer cells." (PMID 35317831, 2022). "HMGB1 has been associated with several hallmarks of cancer, including apoptosis, angiogenesis, invasion, and metastasis such as colon, breast, lung, and prostate cancers." (PMID 35201494, 2021). "In this study, we aim to elucidate the associations of HMGB1 single nucleotide polymorphisms (SNPs) with prostate cancer susceptibility and clinicopathological characteristics." (PMID 33023053, 2020). "In conclusion, our study demonstrated that the HMGB1 SNPs were associated with prostate cancer progression and development." (PMID 33023053, 2020). "We further examined the associations between HMGB1 polymorphisms and prostate cancer susceptibility." (PMID 33023053, 2020). "In this study, we focus on four SNPs of HMGB1, rs1412125, rs2249825, rs1045411, rs1360485, and try to elucidate their associations with prostate cancer susceptibility and clinicopathologic characteristics." (PMID 33023053, 2020). "In conclusion, our results revealed that the HMGB1 SNPs were associated with the clinical status of prostate cancer." (PMID 33023053, 2020). "Our previous study revealed a positive correlation between HMGB1 and RAGE expression in a cohort of patients with primary prostate cancer 14 suggesting that HMGB1 is implicated in the development and/or progression of PCa." (PMID 31410208, 2019). "Its high expression was related to advanced clinical stage as well as high PSA level, which suggest that the expression of RAGE and HMGB1 is associated with the progression and poor prognosis of prostate cancer." (PMID 28487844, 2017). "Increased HMGB2 expression, HMGB1 expression, or coexpression of RAGE and HMGB1 has been associated with prostate cancer progression and has been correlated to poor patient outcome." (PMID 26682011, 2016). "However, the impact of HMGB1 polymorphisms on prostate cancer susceptibility and clinicopathologic characteristics has remained uninvestigated." (PMID 33023053, 2020). "In this study, we demonstrated the associations between HMGB1 polymorphisms and prostate cancer." (PMID 33023053, 2020). "Taken together, these results suggested that the SNPs of HMGB1 might play a more crucial role in tumor progression than carcinogenesis and cancer susceptibility in prostate cancer." (PMID 33023053, 2020). "However, in our current study, the HMGB1 rs1045411 polymorphic variants were associated with advanced pathologic T stage (p = 0.037) and pathologic N1 stage (p = 0.012) in prostate cancer patients." (PMID 33023053, 2020). "The HMGB1 polymorphisms may serve as a predictor of prostate cancer development and tumor progression." (PMID 33023053, 2020). "For HMGB1 rs1412125, the HMGB1 rs1412125 polymorphic TC + CC genotypic variant was significantly associated with a higher D’Amico classification (OR = 1.405, 95% CI = 1.009–1.956; p = 0.044) compared with the TT genotype in 579 patients with prostate cancer." (PMID 33023053, 2020).